STAT3 (signal transducer and activator of transcription 3)
Diseases named in the same sentence as STAT3 in open-access papers (continued):
Sharing a sentence is not in itself a finding about the gene and the disease.
tumor (continued). "Indeed, several studies have indicated that CTLA-8 (IL-17) may stimulate cancer cells to produce angiogenic factors like VEGF, thereby enhancing tumor angiogenesis and growth via STAT3 signaling." (PMID 38812776, 2024). "Moreover, studies utilizing exercise-conditioned serum have revealed that both acute and chronic exercise can influence cancer cell signaling pathways, such as STAT3, Akt, mTOR, and the Hippo tumor suppressor pathway, resulting in reduced cancer cell proliferation and tumor growth." (PMID 39336127, 2024). "Therefore, we examined the impact of STAT3 R609K on tumour growth and CSC maintenance." (PMID 38760429, 2024). "Exosomes made from EL-4 cells and loaded with curcumin and a Stat3 inhibitor can be easily absorbed by microglial brain cells, along with a significant reduction in the production of inflammatory cytokines and elevation in the lysis of tumor cells when administered intranasally." (PMID 38686045, 2024). "Additionally, we revealed that the reduction in tumor growth might be linked to the downregulation of proteins involved in tumor progression like EGFR and STAT3 and anti-apoptotic proteins like Mcl-1 via dinaciclib." (PMID 39668430, 2024). "Indeed, TME subtypes exhibiting fibrosis or a mesenchymal subtype despite high immune infiltrate are unresponsive to pembrolizumab, suggesting that therapeutic targeting the Hippo/Yap1 or STAT3 pathways could potentially enhance anti-tumor immune responses." (PMID 37957015, 2024). "Finally, it was concluded that rosmarinic acid could significantly regulate miR-155 and successively alter IL-6/STAT3 signaling, resulting in the suppression of inflammation in the tumor microenvironment and a possible anti-Warburg effect." (PMID 39519255, 2024). "Furthermore, the protumorigenic effects of STAT3 may involve the induction of miR-21 and miR-181b-1, which, respectively, inhibit the expression of tumor suppressors PTEN and ubiquitin carboxyl-terminal hydrolase CYLD." (PMID 38920657, 2024). "STAT3, in particular, supports cancer cell survival in a metabolically hostile environment by promoting an increase in glycolysis through the Warburg effect, which increases proliferation of these cells quickly draining the area around a tumor of vital nutrients and resources." (PMID 38464736, 2024). "Importantly, the gp130 inhibitor could effectively reverse the tumor-promoting effects of M-BMDMs via IL-6/STAT3 signaling blockage, pointing to its potential therapeutic usage for tumor treatment." (PMID 38274367, 2024). "Based on these discussions, combination targeting the Warburg effects, fatty acid oxidation, and amino acid metabolism regulated by STAT3 with targeting the enzymes involved in metabolic reprogramming in immune cells may have therapeutic potential in tumor patients." (PMID 38245798, 2024). "We genetically confirmed that the effect of systemic BBI608 administration could, at least in part, be due to tumor-cell-intrinsic STAT3 signaling because CRISPR-Cas9-mediated STAT3 deletion in KPT organoids reduced their growth when established as allografts in Stat3WT hosts." (PMID 39128004, 2024). "Moreover, STAT3 may promote tumor progression by modulating the immune response within tumor microenvironments through several signaling pathways, including S1PR1, JAK, and IL-6." (PMID 39738726, 2024). "Taken together, PTPRO can downregulate JAK2/STAT3 phosphorylation, and inhibit oncogenic signals by suppressing expressions of Bcl-2 and Snail; these events may subsequently induce mitochondria-dependent apoptosis and suppress tumor metastasis." (PMID 38182570, 2024).
tumor (continued). "STAT3 was also responsible for the modification of TAMs to the tumor supportive M2-like subtype, while the administration of the STAT3 inhibitor combined with anti-angiogenic agents explicitly decreased microvascular density and tumor proliferation, with a lower number of p-STAT3 macrophages." (PMID 38787372, 2024). "STAT3 can upregulate the expression of miRNAs by directly binding to their promoters, thereby forming a STAT3/miRNA/IL-6 loop or affecting the expression of downstream target genes, ultimately promoting tumor cell proliferation, invasion, and migration, and accelerating tumor growth." (PMID 38172648, 2024). "Signal transducer and activator of transcription 3 (STAT3) is a transcriptional factor involved in almost all cancer hallmark features including tumor proliferation, metastasis, angiogenesis, immunosuppression, tumor inflammation, metabolism reprogramming, drug resistance, cancer stemness." (PMID 38245798, 2024). "Herein, we have investigated the gene and protein expression of GCSF, GCSFR, and STAT3 in 21 tissue biopsy samples and also in tumor associated normal tissue (TANT) samples derived from glioblastoma patients, which revealed significantly differential expression of these genes." (PMID 38538691, 2024). "Therefore, a novel therapeutic approach involving the targeted inhibition of STAT3 combined with the restoration of aberrant immune escape mechanisms within the tumor microenvironment represents a promising strategy that has gained significant traction in ongoing clinical trials." (PMID 38245798, 2024). "Moreover, we found that FXR upregulates IL-6 and IL-6ST expression but not IL6Rɑ, thus suggesting that IL-6/IL-6ST may mediate FXR-modulated Jak2/STAT3 activation and tumor metastasis in NSCLC." (PMID 38360812, 2024). "In addition, STAT3 is a key checkpoint for suppressing anti-tumor immune responses." (PMID 37307835, 2024). "However, it is unclear whether the STAT3/miR-34a/IL-6R loop plays the same role in different tumor cells, which requires further research." (PMID 38172648, 2024). "At the same time, STAT3 upregulates the expression of lncRNAs by binding to their promoters, forming lncRNA/IL-6/STAT3 or lncRNA/IL-11/STAT3 loops, which enhance the drug resistance of tumor cells, or promoting tumor growth and metastasis in vivo and inhibiting tumor cell apoptosis." (PMID 38172648, 2024). "Furthermore, NF-κB and STAT3 interact and cooperate in regulating the interaction of malignant cells and the tumor microenvironment, especially immune cells such as TAMs that release cell-stimulating growth factors and cytokines, including IL-6, IL-10, and TNF-α." (PMID 39061137, 2024). "With its numerous biological functions, the signal transducer and activator of transcription 3 (STAT3) is a key transcription factor, which is closely associated with the apoptotic process of tumor cells and has the ability to increase the resistance of tumor cells to drug toxicity." (PMID 39097833, 2024). "Moreover, evidence implies that several members of the protein tyrosine phosphatase receptor (PTPR) family may contribute to tumor suppression by dephosphorylating STAT3." (PMID 39469621, 2024). "Since STAT3 phosphorylation (p-STAT3) can occur in response to cytokine IL-6 secreted by macrophages during DEN-induced tumor initiation and thus reflect liver inflammation, we investigated whether p-STAT3 levels were altered in Dnajb4–/– mice post-DEN injection." (PMID 39738726, 2024). "The GP130 receptor β subunit is critical in serving as a typical signal for STAT3 in response to IL-6 family, and activation of the complex can induce the expression of enzymes required by cells for cell migration and exomatrix remodeling, which can promote wound healing and tumor progression." (PMID 38320998, 2024).
tumor (continued). "However, no study has elucidated the specific molecular mechanisms by which the CXCL12/CXCR4/ACKR3 axis activates the JAK2/STAT3 pathway, and responses to the CXCL12/STAT3 signal transduction may vary across different tumor types and cell lines." (PMID 38920657, 2024). "Transcription factors involved in inflammation, such as NFκB and STAT3, are known to promote the development and progression of cancer by controlling the expression of genes involved in apoptosis, cell proliferation regulation of angiogenesis, tumor metastasis and invasion." (PMID 38571491, 2024). "Moreover, STAT3 plays a role in DNA damage repair, further increasing tumor radioresistance." (PMID 38967145, 2024). "Furthermore, B. breve lw01 decreased Ki67, p-STAT3, and activated-β-catenin expression in the tumor area, indicating that the bacteria could inhibit tumor cell proliferation and attenuate signaling pathways involved in tumorigenesis in CAC mice." (PMID 38773969, 2024). "Additionally, in vivo experiments demonstrated that treatment with an IL-6 antibody decreases PD-L1 expression in tumor regions by modulating its glycosylation while enhancing JAK1/nonglycosylated PD-L1 association, JAK1-driven Tyr phosphorylation, and STAT3 recruitment." (PMID 39690423, 2024). "Furthermore, GMI’s tumor-suppressive action was achieved by controlling the IL-6/Stat3 pathway." (PMID 39272862, 2024). "Hence, targeting STAT3 may inhibit immunosuppressive interactions between tumor cells and tumor-infiltrating immune cells." (PMID 38339245, 2024). "However, further research is needed to determine whether STAT3 can enhance or inhibit the expression of LncRNAs via other regulatory mechanisms, thereby affecting the biological phenotype of tumor cells." (PMID 38172648, 2024). "Thus, bispecific targeting of mTOR and STAT3 could support increased BSV-induced infiltration of CD8+T cells into the tumor region more significantly than the oncolytic virus treatment itself." (PMID 38886756, 2024). "Intratumoral injection of the obtained NP to tumor-bearing mice resulted in effective sequestration of polypeptide micelles by TAMs and TAM reprogramming into M1 associated with an increase in the ROS level and downregulation of STAT3, followed by apoptosis of tumor tissues." (PMID 38794298, 2024). "Targeting STAT3 in current research offers several advantages, including improving immune dysregulation in the tumor microenvironment, reducing endogenous proliferation of tumor cells, and enhancing the anti-tumor effects of tumor-infiltrating immune cells, among others." (PMID 38650924, 2024). "It was shown that tumor regression in STAT3 shRNA lentivirus Ly3-bearing mice was associated with Caspase-3-dependent apoptosis and significant decrease of STAT3 target genes encoding MCL1, C-MYC, and survivin, as well as inhibition of tumor-promoting environment." (PMID 39528914, 2024). "Moreover, IL-22 may contribute to sorafenib resistance of HCC through activating STAT3/CD155 signaling axis to decrease the sensitivities of tumor cells to sorafenib-mediated direct cytotoxicity and NK cell-mediated lysis." (PMID 38596684, 2024). "Moreover, STAT3 has also been reported to be related to tumor and take part in anti-apoptosis." (PMID 39000312, 2024). "Moreover, STAT3 is also required to maintain constitutive NF-κβ activity in tumour cells." (PMID 38600086, 2024). "Therefore, inhibition of either STAT3/STAT5 signaling or PIM1/FATP2 expression in tumor-bearing mice in vitro could significantly attenuate MDSC-mediated immunosuppressive effects on tumors, thereby improving the anti-tumor response of CD8+ T-cells." (PMID 39227970, 2024). "Therefore, therapeutic activation of STAT3 potentially causes SASP factor modulation and may elevate JUN levels in tumors, thereby restricting tumor progression and enhancing PCa patient survival." (PMID 38811984, 2024).
tumor (continued). "Therefore, MET, as a key molecule for tumor progression, may regulate cell biological functions through the STAT3/Akt signaling pathway." (PMID 38468814, 2024). "Importantly, we also showed that treatment of the LMP1-expressing ΔEBNA2 + Myc tumor-derived “B1” cell line (derived from Donor 1) with the Src kinase inhibitor, dasatinib, not only strongly inhibits the level of constitutive STAT3 tyrosine 705 phosphorylation but also decreases LMP1 expression." (PMID 38620028, 2024). "IL-6 can increase the activity of HIF-1α in tumor cells via STAT3 signaling, and HIF-1α may activate GLUT-1 via the Phosphatidylinositol-3-kinase (PI3K) pathway, which shifts glucose metabolism from oxidative phosphorylation to anaerobic processes (the Warburg effect)." (PMID 39963655, 2024). "Finally, a significant decrease in FoxP3 expression (p = 0.032) and an increase in signal transducer and activator of transcription 3 (STAT3) (p = 0.024) expression were measured in tumor-derived CD3+CD49− cells isolated from the metformin-treated group of mice." (PMID 38892058, 2024). "Furthermore, high molecular weight polysaccharides extracted from Cordyceps sinensis not only enhance the immune function of mice but also induce tumor cell apoptosis through the Cytochrome-c/Caspase8/3 and IL-10/STAT3/Bcl2 pathways, thereby exerting anti-tumor effects." (PMID 38892575, 2024). "Additionally, Stat3 plays a key role in tumor progression and also regulates PD-L1 expression." (PMID 38441416, 2024). "Thus, activated STAT3 helps tumor cells to avoid apoptosis and supports their proliferation." (PMID 38590645, 2024). "Therefore, upregulation of STAT3, ARG1 and IDO in TME of KRASmut tumors in our results might be due to the infiltration of tumor-associated macrophages and tumor-associated neutrophils in TME." (PMID 36831441, 2023). "However, it is also possible that STAT3 in the cells at the tumor boundary may be activated in response to cytokines and growth factors in the tumor microenvironment." (PMID 36446524, 2023). "PepO as always suppressed cancer growth, and PepO still suppressed tumor growth at the presence of colivelin, which was consistent with the result of immunoblot, which suggested that PepO may inhibit a certain molecular upstream of STAT3." (PMID 37925462, 2023). "Interestingly, a recent study has reported that PAR1 exhibited superior protumor capacity via regulating PI3K/AKT/STAT3/NF-κB signaling whereas PAR4-mediated NF-κB activation notably alleviated tumor growth and metastasis, suggesting the opposite effects of PAR1 and PAR4 in tumor modulation." (PMID 38159863, 2023). "TIL-B may sustain tumor progression by providing lymphotoxin (a survival factor that can induce angiogenesis) and by promoting androgen-independent cancer progression by activating NF-κB and STAT3 pathways." (PMID 37046842, 2023). "Therefore, both IL-6 and TNFR2 may contribute to the tumour-promoting roles of STAT3, hence targeting the IL-6-signaling pathway may help to decrease maximally suppressive TNFR2+ Tregs." (PMID 36765633, 2023). "Thus, targeting of either STAT3, or c-Rel, or PI3Kγ reprogram myeloid cells towards an anti-tumour phenotype resulting in the sculpting of a TME towards the support of cytotoxic T cell response and restricting tumour progression in preclinical models of solid cancers." (PMID 36161514, 2023). "JAK2/STAT3 pathway could act as key targets for screening anti-tumor drugs." (PMID 37716993, 2023). "Notably, it inhibits IL-6 and STAT3 signaling pathways, thus impeding tumor growth and metastasis." (PMID 38035069, 2023). "Therefore, inhibitors targeting the JAK/STAT3 pathway may inhibit tumor cell growth and stimulate antitumor immunity." (PMID 37202657, 2023). "Additionally, the STAT3 pathway has been related to immunosuppression in this tumor pathology." (PMID 36936946, 2023).
tumor (continued). "The exact mechanism of tumor initiation is not fully understood, but the downregulation of miR-337-3p likely plays a vital role in it because this microRNA inhibits the activation of the signal transducer and activator of transcription 3 (STAT3) transcriptional factor." (PMID 36835082, 2023). "In addition, the compound can inhibit tumor proliferation and migration by targeting mitochondria, regulating the signal transducer and activator of transcription 3/focal adhesion quinase) signaling pathway (STAT3/FAK), and inhibiting angiogenesis." (PMID 38201542, 2023). "Moreover, STAT3 knockdown diminishes the effect of treatment with metformin in clinically relevant dose on the oxygen consumption rate (OCR) of 22Rv1 tumor cells, hence suggesting a higher protonophoric capacity and resistance to metformin treatment upon STAT3 reduction." (PMID 37573301, 2023). "In addition to regulating the immunological microenvironment, B7-H3 has been reported to activate signaling pathways such as ERK, PI3K, and Stat3 in cancer cells, which may lead to the accelerated cell proliferation and tumor growth." (PMID 36859240, 2023). "However, accumulating evidence from both experimental and clinical studies, suggests that STAT3 may also function as a tumor suppressor." (PMID 37097001, 2023). "Furthermore, we investigated whether the PI3K/Akt and JAK/STAT3 signaling inhibition had any influence on tumor histological features." (PMID 36982542, 2023). "In addition, the elevated exosome miRNA-155 during the co-culture of tumor cells and adipocytes can promote the production and release of adipocytes CCL2 and CCL5 by targeting the SOCS6/STAT3 pathway, thereby regulating the function and polarity of macrophages and promoting tumor progression." (PMID 37666813, 2023). "Therefore, the IL-6/STAT3 signaling pathway is involved in the process of tumor cell resistance." (PMID 37990309, 2023). "Additionally, STAT3 phosphorylation can directly bind to the promoter region of the survivin gene, leading to an upregulation of survivin expression and thereby promoting the survival of tumor cells." (PMID 37892997, 2023). "In addition to its direct effects on tumor cells, STAT3 may play an important role in the regulation of the tumor microenvironment (TME) in GBM." (PMID 37242454, 2023). "Activation of STAT3 may promote the cell cycle process to accelerate tumor cell proliferation." (PMID 37228122, 2023). "In addition, Allam’s team concluded that the higher incidence of colorectal cancer in Naip-/- mice may be related to the inability of Naip-/- mice to suppress the overactivation of STAT3, a transcription factor that promotes tumor growth." (PMID 37020871, 2023). "Moreover, STAT3 shRNA treatment also reduced tumor growth in vivo compared to the control group." (PMID 38067351, 2023). "Initially, it has been viewed as a factor of malignancy, with the IL-6/JAK/STAT3 signaling path having effects such as anti-apoptosis, angiogenesis, and proliferation, while more recent findings have shown that IL-6 also has beneficial roles regarding anti-tumor immunity." (PMID 37892997, 2023). "Supporting this hypothesis, Wang and collaborators showed that overexpression of PCBP1 changes splice site usage at STAT3 exon 23 by binding to an exonic splicing suppressor site, promoting the switch from the oncogenic longer STAT3α isoform to the shorter tumor-suppressive STAT3β isoform." (PMID 37537282, 2023). "Moreover, it may be of great significance to further investigate the possible coaction between the IL‐6/STAT3 signaling pathway and tumor immune efficacy in patients with HCC." (PMID 36951443, 2023). "EPO, acting through the canonical EPO-R or through ephrin-type B receptor 4 (EphB4), an alternative EPO-R, may account for the increased tumor growth and progression through downstream activation of the Src-STAT3 pathway seen in cancer patients treated with ESAs." (PMID 37543610, 2023).